REN (renin)
Diseases named in the same sentence as REN in open-access papers (continued):
Sharing a sentence is not in itself a finding about the gene and the disease.
Hypertension (continued). "The renin-angiotensin-aldosterone system is involved in the occurrence of diabetes and hypertension." (PMID 36675205, 2023). "In patients with hypertension, the stimulated renin-angiotensin system and sympathetic nerve system both decrease the blood flow of renal medulla, accumulating serum uric acid levels." (PMID 36675499, 2023). "There are some potential pathways through which hyperuricemia can induce hypertension such as via endothelial dysfunction, vascular smooth muscle hypertrophy, glomerular hypertrophy, and activation of the renin-angiotensin system." (PMID 36803682, 2023). "The main target organs of hypertension are the heart, kidneys, brain, retina, and arteries, and the activation of the renin-angiotensin-aldosterone system, oxidative stress, and inflammation plays an important role in the pathogenesis of hypertension." (PMID 36845374, 2023). "Primary aldosteronism (PA) is a secondary hypertension characterized by suppression of the renin-angiotensin system due to excessive aldosterone secretion." (PMID 37591913, 2023). "Possible mechanisms of obesity leading to hypertension are insulin resistance, sodium retention, increased sympathetic nervous system activity, activation of renin-angiotensin-aldosterone, and altered vascular function." (PMID 38161531, 2023). "Intrarenal renin-angiotensin system (RAS) seems to have a central role in the development of hypertension in ADPKD since development and expansion of cysts activate intrarenal RAS before than renal fibrosis and renal function decline." (PMID 38027263, 2023). "Patients with MetS often develop hypertension via modulation of the sympathetic nervous system and the renin–angiotensin–aldosterone system, amongst other pathways." (PMID 37626737, 2023). "Another study comparing renin profiling-guided (plasma renin activity) treatment to clinical judgment in uncontrolled hypertensive patients showed equal or better hypertension control while using the renin profile-guided treatment approach." (PMID 36902588, 2023). "There is a substantial overlap between diabetes and hypertension in disease mechanisms such as upregulation of the renin-angiotensin-aldosterone system and inflammation." (PMID 37894687, 2023). "Hypertension is mainly regulated by the renin–angiotensin–aldosterone system (RAAS), with its main mediator being angiotensin II (ANG II)." (PMID 37445727, 2023). "It is known that the renin-angiotensin-aldosterone system is involved in the pathogenesis of hypertension by regulating water-electrolyte and acid-base homeostasis." (PMID 38203261, 2023). "Patients presented with hypertension, hyperkalemia despite average glomerular filtration rate, hyperchloremic metabolic acidosis, and suppressed plasma renin (PR) activity with normal plasma aldosterone (PA) and sometimes failure to thrive." (PMID 37895227, 2023). "The mechanisms underlying hypertension in patients with CKD include increased salt and volume retention, upregulation of the renin-angiotensin system, endothelial dysfunction, and increased sympathetic activity." (PMID 37308973, 2023). "Ethanol-induced hypertension is accompanied by increases in the circulating levels of the catecholamines adrenaline and noradrenaline as well as by increased plasma levels of renin, angiotensin I, angiotensin II, and ACE activities." (PMID 37891892, 2023). "Hypertension was one of the common presenting symptoms in children with WT, due to hypersecretion of renin by the tumor though the number was lower than in a study done in America, where 63% of children presenting with WT had hypertension." (PMID 36864435, 2023). "Available evidence suggests that both hyperactivity of the renin–angiotensin–aldosterone system and insulin resistance are potential mechanisms for hypertension complicated by diabetes." (PMID 37752554, 2023).
Hypertension (continued). "The aim of the study was to clarify the role of the interplay between hypertension and the renin-angiotensin system (RAS) in the pathophysiology of myocardial ischemia/reperfusion (I/R) injury." (PMID 37389123, 2023). "At the same time, sodium retention leads to an expansion of the extracellular fluid volume thought to be responsible for a suppressive action on renin secretion resulting in the characteristic ‘low-renin hypertension phenotype’." (PMID 35414109, 2023). "Some studies suggest that hypertension has disrupted the regulation of the renin‐angiotensin and aldosterone systems through increased adiposity." (PMID 37251525, 2023). "More seldom symptoms like heart failure due to cardiopulmonary overload or secondary hypertension through the activation of renin–angiotensin–aldosterone system (RAAS) have been described." (PMID 37835006, 2023). "In this study, patients with hyperuricemia and hypertension tended to have elevated plasma renin activity, and xanthine oxidase inhibitors reduced plasma renin activity and plasma aldosterone." (PMID 37238926, 2023). "Inflammation, renin-angiotensin system-sympathetic nervous system activation and insulin resistance, endothelial dysfunction Shared genes among hypertension, NAFLD, fibrosis, and inflammation include LEP, ADIPOQ, AHR and TGFB1." (PMID 37664266, 2023). "She had typical clinical characteristics of PA, including hypertension, hypokalemia, and high plasma aldosterone concentration with suppressed renin." (PMID 38077309, 2023). "The role of the renin-angiotensin-aldosterone system in arterial hypertension induced by VEGF inhibitors is minor compared with essential hypertension." (PMID 36836722, 2023). "In a rat model of hypertension disease, Piezo2 activation was observed in mesangial cells, renin cells, and perivascular mesenchymal cells, implying its contribution to renal fibrosis." (PMID 37958966, 2023). "Previous studies have shown that the activation of the RAAS is involved in hypertension formation and that renin is a key factor in RAAS activation." (PMID 36675205, 2023). "Due to refractory potassium depletion and hypertension, workup for hyperaldosteronism revealed renal potassium wasting, inappropriately normal plasma renin levels, and almost undetectable aldosterone levels." (PMID 36843745, 2023). "The renin-angiotensin system (RAS) plays a pivotal role in regulation of cardiovascular diseases including hypertension." (PMID 37854465, 2023). "Another principle that implicates hypertension in the development of liver disease is via the renin-angiotensin system (RAS)." (PMID 37107538, 2023). "Apparently vasoconstriction of the arterial bed seems to be a major reason for hypertension, and the sympathetic nervous system and renin–angiotensin aldosterone system seem to be major factors involved in the pathogenesis of hypertension." (PMID 36986445, 2023). "In hypertension, the renin–angiotensin–aldosterone system (RAAS) is almost always activated, and is usually also causally involved in the development of hypertension." (PMID 36979025, 2023). "For instance, inhibitors of the renin-angiotensin system, already widely utilized in the treatment of arterial hypertension, have demonstrated the ability to inhibit CAFs and collagen synthesis." (PMID 37686288, 2023). "A 52-year-old woman was admitted to our hospital with suspected PA based on the presence of hypertension, spontaneous hypokalemia, and a high aldosterone-to-renin ratio." (PMID 36797699, 2023). "History of hypertension was present in 12 (50%) of patients who were treated with renin-angiotensin system blockers (n = 8), calcium-channel blockers (n = 5), diuretics (n = 3) and beta-blockers (n = 3)." (PMID 37111106, 2023). "These activating variants have also been described in male patients with familial dominant forms of hypertension developing from the first decades of life, with suppressed renin and aldosterone." (PMID 37537162, 2023).
Hypertension (continued). "Both animal and human studies have demonstrated that lead exposure can lead to hypertension by increasing renin–angiotensin–aldosterone system reactivity, reducing prostacycline production, and enhancing oxidative stress." (PMID 37574566, 2023). "The renin-angiotensin-aldosterone system is an important target for anti-hypertension and reversing LVH." (PMID 36984599, 2023). "Renin-angiotensin system inhibitors (RASi) are widely used to treat hypertension and related complications." (PMID 37901395, 2023). "Hypertension is a major risk factor for cardiovascular disease (CVD) and is associated with increased bone loss due to excessive activity of the local renin-angiotensin system (RAS)." (PMID 37795376, 2023). "Nearly 70% of hypertension onsets in adults can be attributed to obesity, primarily due to sympathetic overdrive and the dysregulated renin-angiotensin system." (PMID 36831252, 2023). "In patients with arterial hypertension, renin activity was found to be inversely related to 1,25(OH)2D3 levels." (PMID 36788562, 2023). "Similarly, the mechanisms associated with the development of obesity and hypertension include insulin resistance, and the remaining mechanisms include inflammation, oxidation, active stress, and excessive activation of the sympathetic nervous system and the renin–angiotensin–aldosterone system." (PMID 36690699, 2023). "In addition, chronic hyperuricemia, the activation of the renin–angiotensin system, and the inhibition of nitric oxide synthetase may cause the narrowing of the renal vasculature, thereby increasing the risk of atherosclerosis and hypertension." (PMID 38132235, 2023). "A multitargeted interaction-based degree algorithm and a phylogenetic tree of pathways showed that the NR3C1, REN, PPARG, and CYP11B1 hub genes were consistently modulated by Υ-sitosterol to reduce hypertension and related risk factors." (PMID 37571339, 2023). "Human subjects and animal models with this form of hypertension have a reduced activity of the renin–angiotensin system leading to chronic suppression of plasma angiotensin II (ANG II) levels." (PMID 37107157, 2023). "We found that the concentration of renin in serum was increased in patients with diabetes and hypertension." (PMID 36675205, 2023). "In this GLUT4 +/- mice model, maternal high-fat-diet-induced hypertension in offspring was accompanied by increased renal gene expression of renin and the AT1R." (PMID 37375602, 2023). "In certain studies, male OVE26 mice were crossed with female TTRhRen mice to obtain OVE26‐TTRhREN double transgenic mice, showing dual additive effects of renin‐dependent hypertension and diabetes." (PMID 37723622, 2023). "Vitamin D plays a role in suppressing renin-angiotensin-aldosterone activity, improving function of vascular wall and alleviating vascular oxidative stress to regulate hypertension." (PMID 37855616, 2023). "Lastly, obesity-related fat accumulation around the kidneys can physically compress them, resulting in the activation of the renin-angiotensin-aldosterone system, a mechanism leading to hypertension." (PMID 37849941, 2023). "Hypertension leads to some changes that can affect the severity of COVID-19, such as dysregulation of the renin-angiotensin-aldosterone system, gastrointestinal dysfunction, and imbalance in inflammation and immune response." (PMID 37746500, 2023). "By the very mechanisms of these conditions, serum aldosterone is elevated, renin suppressed, and hypertension is significant." (PMID 35585366, 2023). "Many of these models have been developed using etiological factors thought to be responsible for human hypertension, such as genetic factors, excessive salt intake, and disorders of the renin-angiotensin-aldosterone system." (PMID 38203261, 2023).
Hypertension (continued). "Inflammatory cytokines can strongly induce high blood pressure, which plays a role in regulating blood pressure due to the disruption of the renin-angiotensin system, vascular inflammation, and the reduction of NO production." (PMID 37841398, 2023). "The following examples are the physiological processes typically involved in the emergence of essential hypertension: cardiac output, peripheral resistance, autonomic nervous system, renin–angiotensin system, and endothelial dysfunction." (PMID 37887299, 2023). "Circulating EO is elevated and positively correlated with BP in a variety of hypertensive states, including essential hypertension and secondary hypertension, especially in the normal renin or low-renin essential hypertensive patients." (PMID 36629529, 2023). "The phenotypic feature of essential hypertension (EH) involves different profiles of nighttime decreases in blood pressure (BP) due to an enhancement of the activity of the renin–angiotensin–aldosterone system (RAAS) at night." (PMID 38066794, 2023). "Chronic high blood pressure (BP) can lead to arterial wall damage by mechanical stress, endothelial dysfunction, increased inflammation, oxidative stress, and renin–angiotensin–aldosterone system (RAAS) activation." (PMID 38037153, 2023). "Downregulation of the activity of renin over the course of hypertensive disease during pregnancy suggests a compensatory response to high blood pressure, rather than a primary event in the pathogenesis of the disease." (PMID 37628909, 2023). "ACE2 role is to counteracts angiotensin II effects in excessive renin-angiotensin system activation in certain circumstances as hypertension (HTN) and congestive heart failure (CHF)." (PMID 36627579, 2023). "Most of the suggested theories for salt-induced high blood pressure involve impaired function in either the kidneys or the endocrine system, with a particular focus on the renin-angiotensin-aldosterone system (RAAS)." (PMID 37416924, 2023). "HUS patients are prone to develop high blood pressure likely due to intravascular volume expansion and/or the activation of the renin-angiotensin-aldosterone system (RAAS) secondary to ischemia." (PMID 36628001, 2023). "To study the development of microalbuminuria (MAU) in essential hypertension (EHT), we investigated the association of MAU with central blood pressure (CBP), direct renin concentration (DRC), plasma aldosterone (PA), and uric acid (UA)." (PMID 37848834, 2023). "Changes in the activity of the renin–angiotensin–aldosterone system are responsible for a stable shift in the regulation of the cardiovascular system in essential hypertension (EH)." (PMID 38066794, 2023). "The truncated protein in individuals with the FF genotype is thought to promote the development of essential hypertension by increasing the production of renin and angiotensin II." (PMID 36788562, 2023). "In the 1970’s, established that approximately 25% of humans with essential hypertension exhibit low plasma renin activity." (PMID 37293629, 2023). "In contrast, spontaneously hypertensive rats (SHRs), an animal model for essential hypertension with high-renin, also display alterations in salt-taste responses." (PMID 36771242, 2023). "Hypertension can stimulate the activation of the renin–angiotensin–aldosterone system (RAAS), a hormone system responsible for regulating BP and fluid balance." (PMID 38037153, 2023). "These processes exacerbate atherosclerotic plaques leading to vascular injury and constriction and infiltration of Th17 cells in the kidney with production of IL-17A activates the renin-angiotensin aldosterone system (RAAS) resulting in high blood pressure." (PMID 37089429, 2023). "In the mice, in fact, with null vitamin D receptor (VDR-null) the expression of renin and angiotensin II has increased and it leads to hypertension, cardiac hypertrophy, and an increase in the intake of water." (PMID 36313775, 2022).
Hypertension (continued). "For patients with new-onset VSPi-induced hypertension, the current guidelines recommend medications targeting the renin–angiotensin–aldosterone (RAAS) pathway such as ACE inhibitors, ARBs, and dihydropyridine CCBs as first-line therapy." (PMID 35201530, 2022). "Therefore, increased insulin resistance, higher body mass index, and increased risk of obesity have been observed among c.825C>T polymorphism carriers in European study populations, and these findings could contribute to low renin hypertension among T-allele carriers." (PMID 36077181, 2022). "Hypertension in patients with repaired CoA is multifactorial and related with anatomical residual arch gradients as well as alterations in renin–angiotensin and baroreceptor systems with combined long-term impacts on arterial wall and LV mass." (PMID 35944231, 2022). "Lead can induce hypertension in rats, and lead acts on many parts of the cardiovascular system, possibly affecting blood pressure through the renin-angiotensin system." (PMID 35782949, 2022). "We divided the sample by renin level into two groups, a high-renin group and a low-renin group, and the low-renin group showed more incidence rates of new-onset hypertension (35.3%) than the high-renin group (26.5%)." (PMID 35448080, 2022). "In terms of the pathophysiologic mechanisms, numerous neurohormonal factors lead to the development of HF from hypertension, including the activation of the sympathetic nervous system and elevated levels of renin and aldosterone." (PMID 36196463, 2022). "It has long been known that the renin-angiotensin system (RAS) is essential in the development of hypertension." (PMID 36123994, 2022). "Pharmacological management includes renin-angiotensin system blockade as first-line therapy for hypertension and proteinuria." (PMID 33677691, 2022). "In a previous four-year follow-up study conducted in Korea, the low-renin group had a higher incidence of hypertension than the high-renin group, which was noticeable in the individuals with high salt intake." (PMID 35448080, 2022). "Reninoma typically shows clinical features secondary to the overproduction of renin, including hyperaldosteronemia, hypokalaemia, and metabolic alkalosis, in addition to hypertension." (PMID 35303838, 2022). "Age, blood pressure, heart rate, incidence of coronary artery disease and hypertension, and use of calcium-channel blockers and renin-angiotensin-aldosterone inhibitors were significantly different between the sexes." (PMID 36233777, 2022). "This study focuses on pseudohypoaldosteronism type II (PHA II), a form of Mendelian hypertension that features hyperkalemic acidosis and low plasma renin levels." (PMID 35093948, 2022). "According to experimental evidence, the renin–angiotensin system has a role as a mechanism for hypertension triggered by estrogen." (PMID 34991554, 2022). "In addition, various genes that regulate the renin-angiotensin system and adrenergic system, estradiol, testosterone, estrogen/androgen ratio, and environmental factors such as age, BMI, insulin, oxidative stress, and cholesterol affect the risk of hypertension among postmenopausal women." (PMID 36003912, 2022). "Hypertension directly triggers the remodeling of cardiac walls through increases in the cardiac afterload and indirectly through the heightened activity of the renin-angiotensin system." (PMID 35725371, 2022). "Extracellular succinate has been shown to play an important role in enhancing inflammation, inducing tissue fibrosis and regulating renin-angiotensin and hypertension." (PMID 36344992, 2022). "As per the findings of that study, the independent predictors of AFib development were age, left atrial diameter, hypertension, prior statin and renin-angiotensin system blocker use, and prior AFib history." (PMID 35761924, 2022).